ERBB4 (erb-b2 receptor tyrosine kinase 4)
Diseases named in the same sentence as ERBB4 in open-access papers (continued):
Sharing a sentence is not in itself a finding about the gene and the disease.
breast carcinoma (continued). "Upregulated genes ERBB3 (HER3) and ERBB4 (HER) belong to the HER family of receptors and are implicated in breast cancer." (PMID 37091785, 2023). "Depending on the dataset, ERBB4 fusions were most often found in ovarian cancers, breast cancers or NSCLC." (PMID 37168365, 2023). "Overexpression of ERBB3 is also common in human breast cancers and likely enhances ERBB1-signaling, whereas both the overexpression and downregulation of ERBB4 expression has been reported in mammary tumors." (PMID 37219601, 2023). "Taken together, FGFR2, RET, and ERBB4 are potential targets of HON for overcoming ER+ breast cancer resistance to TAM." (PMID 36601474, 2022). "Downregulation of ERBB4 is supported by a previous study that downregulation of ERBB leads to the increased sensitivity of breast cancer cells to TAM." (PMID 36601474, 2022). "A genetic alteration study of potential target genes revealed MMP16 and ERBB4 as the genes with the highest alterations among the breast cancer samples." (PMID 36601474, 2022). "Collectively, these data in HER2+ breast cancer cells demonstrate that NRG4 activates ERBB4 and boosts the anti-proliferative effects of anti-ERBB2 agents." (PMID 35664762, 2022). "We also observed that HER2-enriched breast cancers express intermediate ERBB4 mRNA levels compared to luminal and triple-negative/basal-like subgroups, which displayed the highest and the lowest levels, respectively." (PMID 35664762, 2022). "Our data show that luminal A/B and normal-like breast cancer subtypes display the highest levels of ERBB4 expression, the HER2-enriched subtype shows intermediate levels, whereas the lowest levels are detected in the basal-like breast subtype." (PMID 35664762, 2022). "We also analyzed the expression levels of ERBB4 in breast cancer patients stratified for clinical subtypes." (PMID 35664762, 2022). "A study by Tovey and colleagues compared antibody detection of ErbB4 in estrogen receptor-positive breast cancer patients." (PMID 36119496, 2022). "We then analyzed ERBB4 expression levels in breast cancer patients stratified for molecular subtypes (PAM50)." (PMID 35664762, 2022). "Whilst there is a wealth of literature on the potential role of ErbB4 in breast cancer, melanoma, and lung cancer, relatively little is known about its potential role in brain cancers." (PMID 36119496, 2022). "Next, we characterized the mRNA expression of ERBB4 in publicly available datasets of breast cancer specimens and normal breast tissue (technical details are provided in the “Material and methods” section)." (PMID 35664762, 2022). "Inspired by these clinical data, we tested the activation of ERBB4 by Neuregulins as a potential anticancer strategy for HER2+ breast cancers." (PMID 35664762, 2022). "As was reported by us and others, another tyrosine receptor kinases pathway which depends on the WWOX expression gene is ERBB4 signaling in breast cancer cells." (PMID 35290621, 2022). "Expression of PTK6 is often found co-amplified with members of the EGF receptors including ERBB4 in breast cancer." (PMID 34136393, 2021). "Previous studies have demonstrated that several enhancers interact with the ERBB4 promoter, implying that the elimination of this area can have an impact on ERBB4 expression, thereby contributing to breast cancer." (PMID 35011637, 2021). "In breast cancer, ERBB4 acts as a tumor suppressor, regulating cell proliferation, development, and differentiation." (PMID 35011637, 2021). "ESR1 positively correlates with DNAJC12 and ERBB4, and DNAJC12 also positively correlates with ERBB4 in breast carcinoma." (PMID 33718139, 2021). "The cBioPortal tool was employed to analyze the TCGA database for correlativity among the expression of ESR1, DNAJC12, and ERBB4 in breast carcinoma." (PMID 33718139, 2021). "Nonetheless, as compared to the enhancer’s annotations in HMEC cells, a set of enhancers found upstream of ERBB4 was found to be deleted in T47D breast cancer cells." (PMID 35011637, 2021).
breast carcinoma (continued). "ESR1 is positively correlated with DNAJC12 and ERBB4, and DNAJC12 is positively correlated with ERBB4 in breast carcinoma." (PMID 33718139, 2021). "We find such an example in the breast cancer cell line T47D, where a 130-kbp heterozygous deletion links a distal enhancer to the ERBB4 promoter and results in the activation of this well-known oncogene." (PMID 32728046, 2020). "Another seven genes (CDH13, CDH7, CTNNA2, ERBB4, GRIK1, PCDH15, and TCF7L2) were reported as associated with the breast cancer by recent GWA studies." (PMID 28615668, 2017). "Erbb4 appears to be an oncogene in breast cancers, and Erbb2 has been suggested to help Erbb4 carry out the oncogenic activities." (PMID 28212608, 2017). "Recent studies show the significant role of both ErbB3 and ErbB4 as alternative targets for the treatment of breast cancer patients suggesting a pan-ErbB inhibitor strategy that is able to interfere the cross-talk between the various ErbB receptors." (PMID 27832067, 2016). "Patients in the validation set with high ERBB4-expressing breast cancer (cut-off value (log2 scale) = 1.3, the same as that used for the training set) had worse DRFS rates than those with low expression (5Y DRFS, low vs. high: 69.4 % vs. 44.7 %, p = 0.053)." (PMID 26907936, 2016). "On the other hand, activation of ERBB4 leads to cell cycle arrest, differentiation and apoptosis of breast cancer cells." (PMID 26701850, 2016). "Patients with breast cancer showing co-expression of ERBB4 and ER have fewer recurrences and improved survival compared to patients diagnosed with ER-positive breast cancer without ERBB4 expression." (PMID 26907936, 2016). "On one hand, ERBB4 promotes growth of human breast cancer cells and promotes metastasis in Ewing sarcoma." (PMID 26701850, 2016). "In agreement with previously published studies, stronger expression of ERBB4 in breast cancer cohorts correlated with better prognosis." (PMID 26479444, 2015). "While ERBB1, ERBB2 and ERBB3 are often overexpressed or activated in breast cancer, and are oncogenic, the role of ERBB4 in breast cancer is uncertain." (PMID 25516216, 2014). "Treatment with ErbB4-targeted monoclonal antibody suppresses the growth of breast cancer cells, suggesting a possible oncogenic role of ErbB4 in breast cancer." (PMID 25036186, 2014). "Correlative biomarker studies have implied either pro-tumorigenic or anti-tumorigenic activity of ERBB4 in breast cancer." (PMID 25516216, 2014). "Despite of active research on ErbB4 biology in normal mammary tissue and breast cancer, significance of ErbB4 for breast carcinogenesis is still poorly understood." (PMID 25036186, 2014). "Here, we analyzed the frequencies and prognostic value of two ERBB4 promoter variants, −782G>T and −815A>T in a large phase III clinical trial data set of high-risk early breast cancer patients (n = 1010)." (PMID 25036186, 2014). "HRG is a ligand for ErbB3 and ErbB4 and has also been reported to promote the invasive behavior of breast cancer cells in vitro." (PMID 23937725, 2013). "mAb 1479 also significantly blocked ErbB4 cleavage in breast cancer cell xenografts in vivo, and the inhibition of cleavage was associated with suppression of xenograft growth." (PMID 22761786, 2012). "Using this ELISA we demonstrate that ErbB4 shedding is significantly enhanced in serum collected from patients diagnosed with early breast cancer compared to healthy individuals." (PMID 22761786, 2012). "Proteolysis-dependent signaling of ErbB4 has been proposed to be enhanced in breast cancer, mainly based on immunohistochemical localization of intracellular epitopes in the nuclei." (PMID 22761786, 2012). "Frequency of cancer ErbB4 expression and subcellular localization of ErbB4 were similar in the current series to the breast cancer series studied previously using anti-ErbB4 immunohistochemistry." (PMID 22761786, 2012).
breast carcinoma (continued). "In conclusion, our findings indicate that regulated processing of ErbB4 is biologically relevant in breast cancer." (PMID 22761786, 2012). "Analysis of 238 breast cancer patients demonstrated elevated quantities of ErbB4 ectodomain in the serum (≥40 ng/mL) in 21% of the patients, as compared to 0% of 30 healthy controls (P = 0.002)." (PMID 22761786, 2012). "ErbB3 has been identified as a key partner for ErbB2, with this receptor heterodimer being identified as an oncogenic unit in breast cancer cells, whilst overexpression of ErbB4 has also been shown to promote growth of human breast cancer cells." (PMID 21396094, 2011). "Western blots for ERBB4 demonstrated a single strong band at the predicted size for the full-length ERBB4 protein (180 kDa) only in the breast cancer cell line T47D-positive control." (PMID 21364580, 2011). "For example, both ErbB3 and ErbB4 have been found to localise not only at the membrane but also within the nucleus in breast cancer cells." (PMID 21396094, 2011). "The coding region of full-length ErbB4 cDNA was originally identified from sequencing of plasmids containing ErbB4 inserts from a human MDA-MB-453 breast cancer cell line and pEV7-HER4, from fetal human brain tissue." (PMID 20886074, 2010). "The EGFR and ERBB3 are overexpressed in 50–70% of lung, colon and breast carcinoma; ERBB2 is overexpressed in 30% of breast cancer patients; ERBB4 is expressed in 50% of breast cancer patients and 22% of colon cancer patients." (PMID 20010942, 2010). "As well, estrogen was seen to promote an association between extranuclear ER-α and the EGFR family member ERBB4 in the T47 D breast cancer cell line." (PMID 20809984, 2010). "Two SNPs in MSR1 (rs9325782, GEE p = 0.008 and rs2410373, FBAT p = 0.021) were associated with prostate cancer and three SNPs in ERBB4 (rs905883 GEE p = 0.0002, rs7564590 GEE p = 0.003, rs7558615 GEE p = 0.0078) were associated with breast cancer." (PMID 17903305, 2007). "The preferred heterodimerisation partner for the Erbbs (including Erbb4) is Erbb2, which has profound links to breast cancer and which has been therapeutically targeted with positive clinical results." (PMID 16933995, 2006). "Another ligand for Erbb4, Nrg1, can induce migration of breast cancer and melanoma and cells in vitro." (PMID 16933995, 2006). "Interestingly, a study conducted on Lu Lu Tong isolates identified 13 triterpenoids with potential anti-breast cancer effects, via inhibition of multiple protein targets such as ErbB4 and EGFR." (PMID 38371501, 2024). "Adding a monoclonal antibody of ErbB4 to non-small-cell lung cancer cells expressing ErbB4 can inhibit cell growth and promote cell apoptosis, deletion of ErbB4 can result in proliferation of human breast cancer cells, and these all indicate that ErbB4 has a tumor suppressive effect." (PMID 37800117, 2023). "MABs against ERBB4 have been developed or are in development and will be soon brought into clinical trials; they reduce the rate of proliferation of neuregulin‐1‐dependent breast cancer cells in vivo." (PMID 37341059, 2023). "Apart from BTK inhibition, ibrutinib also blocks the activation of EGFR, human epidermal growth factor receptor 2 (HER2), Erb-B2 receptor tyrosine kinase 3 (ErbB3), and Erb-B2 receptor tyrosine kinase 4 (ErbB4), which results in increased apoptosis of breast cancer cells." (PMID 36903645, 2023). "Indeed, we did not appreciate significant differences in relapse-free survival of basal-like and luminal B breast cancer patients stratified for ERBB4 expression levels." (PMID 35664762, 2022). "On the other hand, ERBB family receptor tyrosine kinases are commonly overexpressed in breast cancers, in particular, ErbB2 or HER2/neu amplification constitute a major breast cancer subtype found in 15–30% of breast cancers while ErbB4 overexpression is less common." (PMID 35846378, 2022). "Consistently, ERBB4 was more expressed in breast cancer cell lines of the luminal subgroup." (PMID 35664762, 2022).
breast carcinoma (continued). "Indeed, a previous study reported that elevated ERBB4 levels correlate with increased relapse-free survival in all breast cancer clinical subtypes, including triple-negative breast cancer." (PMID 35664762, 2022). "Based on the positive association between higher ERBB4 levels and longer relapse-free survival of HER2+ breast cancer patients, we performed additional analyses for the evaluation of the role of ERBB4 in HER2+ breast cancers, which to date is still unclear." (PMID 35664762, 2022). "Additionally, HECW1 has been found to negatively regulate ErbB4 protein expression via ubiquitin-mediated degradation in breast cancer." (PMID 34348693, 2021). "The study revealed that triterpenoids from Liquidambaris Fructus might exert anti-breast cancer effect by directly inhibit multiple protein targets and signaling pathways, especially ErbB4 and EGFR and related pathways." (PMID 33246450, 2020). "On the contrary, low expression of ERBB4 protein or mRNA levels have been correlated with shorter overall survival or poor prognosis in hepatocellular carcinoma, breast cancer, and triple-negative and Her2 positive breast cancer." (PMID 32316671, 2020). "GO enrichment analysis indicated that inhibition of protein tyrosine kinases autophosphorylation might be the primary mechanism for the anti-breast cancer effect of the triterpenoids, and ErbB4 and EGFR were the most relevant targets." (PMID 33246450, 2020). "Indeed, overexpression of a cleavable ERBB4 isoform promotes breast cancer cell growth both in vitro and in vivo, and an antibody specifically blocking ERBB4 cleavage suppresses it." (PMID 30166589, 2019). "In addition to promoting differentiation and growth, the ERBB4 ICD has been demonstrated to induce apoptosis in various breast cancer cell lines." (PMID 30166589, 2019). "Our data also revealed upregulation of not only ERBB2, but also ERBB3 and ERBB4 in breast cancer." (PMID 31620367, 2019). "In the case of breast cancer, where certain ERBB4 isoforms activate YAP target genes to promote cell proliferation and invasion, SSOs may be used to steer splicing towards the production of ERBB4 isoforms that do not result in YAP transcriptional output." (PMID 29534050, 2018). "Furthermore, the expression of WWOX and ERBB4 was significantly lower in tissues derived from lymph node matched metastases than primary breast cancer tissues." (PMID 30211123, 2018). "We sought to determine whether high ErbB-4 mRNA levels or elevated/positive HER4 protein expression could be a prognostic marker for breast cancer." (PMID 27736797, 2016). "The association between the ERBB4 −815A/T polymorphism and clinical outcome serves the hypothesis that ErbB4-targeted therapy could be beneficial for a subgroup of breast cancer patients in the adjuvant setting." (PMID 25036186, 2014). "Failure to account for isoform-specific functions in previous studies may account for conflicting reports on the role of ERBB4 in breast cancer." (PMID 25516216, 2014). "The role of ERBB4 gene variation in breast cancer has been less extensively studied." (PMID 25036186, 2014). "Although the functional consequences of ERBB4 breast cancer mutations have not been studied, one ERBB4 kinase domain mutation (E872K) initially found in breast cancer has later been shown to be functionally active in metastatic melanoma." (PMID 25036186, 2014). "Furthermore, a monoclonal antibody mAb 1479, that specifically targets the cleavable ErbB4 JM-a isoform, has been shown to suppress breast cancer cell growth in vitro." (PMID 22761786, 2012). "According to the papers, nuclear cleavable ErbB-4 is associated with shorter survival than cell surface ErbB-4 in the estrogen receptor-positive subset of breast cancer patients, suggesting that the subcellular localization of ErbB-4 is correlated with clinical outcome." (PMID 22520625, 2012).
breast carcinoma (continued). "In the present study, we have investigated whether induction of ErbB3 and/or ErbB4 may provide an alternative resistance mechanism to antihormonal action in a panel of four oestrogen receptor (ER)-positive breast cancer cell lines." (PMID 21396094, 2011). "Similarly, an association between the expression of ErbB4 and a favourable clinical outcome has been reported in some clinical studies, whilst other researchers have suggested that ErbB4 expression might be a marker of a poorer outcome in some breast cancer patients." (PMID 21396094, 2011). "The ErbB family (ErbB1/EGFR, ErbB2/HER2, ErbB3/HER3 and ErbB4/HER4) of receptor tyrosine kinases (RTKs) is known to drive both formation and progression of a number of commonly occurring cancers, including breast cancer, due to the normal role of these RTKs in regulating cell growth and survival." (PMID 18841159, 2008). "The epidermal growth factor receptor (EGFR) family, including ErbB4, plays critical roles in various cancers, notably breast cancer (BC)." (PMID 39949609, 2024). "Alterations in the ErbB family (namely ErbB1 (EGFR/HER1), the orphan receptor ErbB2 (HER2 or Neu), ErbB3 (HER3), and ErbB4 (HER4)) have been associated with BC incidence and poor prognosis and mutations of ErbB effectors are among the most common genetic abnormalities associated with breast cancer." (PMID 36233192, 2022). "Thus, we decided to test whether the activation of ERBB4 signaling by neuregulins may restrain the aggressiveness of HER2+ breast cancers, if ERBB2 is inhibited by anti-HER2 agents." (PMID 35664762, 2022). "Interestingly, it was reported that HIF2α enhances autocrine growth signaling through AREG and EGFR/ErbB4 expression in breast cancer cell lines, strengthening this hypothesis." (PMID 36230857, 2022). "In previous study we found the anti-breast cancer effect of betulonic acid, and this study revealed that LF triterpenoids might exert anti-breast cancer effect by directly inhibit multiple protein targets and signaling pathways, especially ErbB4 and EGFR and related pathways." (PMID 33246450, 2020). "Other genes, such as ESR1 (logFC 6.02); GATA3 (logFC 3.88); ERBB4 (logFC 3.0); AR (logFC 2.94); CCDC170 (logFC 2.79); MAPT (logFC 2.45); PGR (logFC 2.91); PIP (logFC 5.42) in immunoglobulin G-binding protein from this cluster were closely associated with breast cancer progression." (PMID 32182819, 2020). "In addition, ERBB4 overexpression was reported to be associated with favorable prognosis in breast cancer patients, especially in cases of ER-positive and/or ERBB2-amplified breast cancer." (PMID 26907936, 2016). "However, the prognostic or predictive role of germ-line or somatic ERBB4 mutations in breast cancer has not been addressed." (PMID 25036186, 2014). "Heregulin, a ligand of HER receptors and more specifically of ErbB3 and ErbB4, which is essential for ErbB2 phosphorylation in response to heregulin, is involved in the progression of different types of human cancers and induces the spread of breast cancer cells in vivo." (PMID 22952755, 2012). "Furthermore, blockade of ErbB3 expression using an artificial transcription factor, E3, inhibits breast cancer cell growth and targeted downregulation of ErbB4, using either ribozymes or small interfering RNA, can reduce the growth of MCF-7 and T47D cell lines both in vitro and in vivo." (PMID 21396094, 2011). "ERBB4 is a member of the HER-2 family and its knockdown activates apoptosis in lapatinib-resistant and trastuzumab-resistant breast cancer cells, indicating its role in tumor progression." (PMID 37175499, 2023). "Six target genes (FGFR2, RET, ERBB4, SOX2, FN1, and MMP16) were analyzed across breast cancer studies using the cBioPortal to assess genomic alterations." (PMID 36601474, 2022). "Clinical data supported a link between ERBB4 and increased survival in luminal and HER2+ breast cancer patients." (PMID 35664762, 2022).